FGF23 (fibroblast growth factor 23)
Diseases named in the same sentence as FGF23 in open-access papers (continued):
Sharing a sentence is not in itself a finding about the gene and the disease.
tumor (continued). "The results of spatial phenotyping of MC interactions with other representatives of the tumour microenvironment, including atypical FGF23-producing cells, revealed an almost complete absence of direct contact with tumour cells." (PMID 40981193, 2025). "Repeat testing with an intact FGF-23 assay demonstrated elevation (92 pg/mL), supporting a diagnosis of TIO despite the remote FCM exposure and negative NetSpot scan (Etwok Inc., Dover, DE, United States) for tumor localization." (PMID 40951211, 2025). "Since he was deemed not a surgical candidate based on his tumor location, our patient was treated with burosumab, which is a monoclonal antibody that targets and blocks the activity of FGF23." (PMID 40922882, 2025). "Elevated serum FGF23 levels can diagnose TIO, with octreotide sestamibi scans locating the tumor." (PMID 39185431, 2024). "Possible explanations for the longer delay in the group with the largest tumor are: the lack of FGF23 measurements, and the lack of experience of the treating physician in recognizing this condition." (PMID 35857061, 2022). "This treatment is also indicated in cases where the FGF23 producing tumor cannot be located, complete tumor removal is not possible or in patients with severe comorbidities." (PMID 35352187, 2022). "In immunohistochemistry, expression of FGF23 was shown in the cytoplasm of the osteoblast-like tumor cells, CD56 was diffusely positive on the cell membrane of the tumor cells and SATB2 was diffusely positive on the tumor cells." (PMID 36686800, 2022). "In summary, the impact of vitamin D3 supplementation or calcitriol administration on blood flow or CAFs and lung NFs is not visible in less invasive tumor models, such as 67NR, despite induced changes in plasma and/or tumor tissue concentrations of OPN, CCL2, TGF-β, VEGF, and FGF23." (PMID 36230508, 2022). "Pathological manifestations of nonspecific tumor-like changes, accompanied by the positive expression of FGF-23, increase the odds of diagnosing PMT." (PMID 36615052, 2022). "Therefore, to examine the regulatory mechanism of FGF23 production in TIO-related tumors, we performed an RNA sequencing analysis using the responsible tumor in the parotid gland from a patient with TIO." (PMID 30627598, 2019). "Symptoms of TIO can therefore be unambiguously attributed to over-expression of FGF23 and/or other tumour-secreted phosphatonins, without potential confounding contributions to the clinical phenotype from mutated genes." (PMID 30808384, 2019). "Upregulated expression of various canonical FGFs (including FGF1, FGF2, and FGF 6–9) derived from tumor cells or stromal cells induces tumor progression in various cancers; however, the effects of circulating hormone-like FGFs (such as FGF19, FGF21, and FGF23) on tumors are unclear." (PMID 31408968, 2019). "Increased expression of VDR and FGF23 relative to other VRS components is interesting, especially in the context of increased Runx2 expression as previously observed in the same OS-core type, and also in the tumor tissue isolated from the BOOM model." (PMID 28300755, 2017). "Bone-metastatic breast and other cancer cell lines often express klotho, but tumor responses to FGF23 have not been reported." (PMID 25944690, 2015). "Tumor cells were not tested in these papers for the major physiological function of klotho to mediate cellular responses to FGF23." (PMID 25944690, 2015). "They speculated that, in such instances, the tumor may secrete inactive or insufficient FGF-23, or possibly none at all." (PMID 40406261, 2025). "This could be caused in part by somatic differentiation of the FGF23-negative fraction comprising 90–95% of the tumors, as also illustrated by the similar expression pattern of OCT4 within the tumor." (PMID 40279260, 2025). "Numerous PET/CT scans failed to localize an FGF-23-producing tumor." (PMID 41583152, 2025).
tumor (continued). "The findings may be applied in translational medicine to develop novel algorithms for personalised therapy in patients with FGF23-secreting tumours, offering an alternative when surgical removal of the tumour is not feasible." (PMID 40981193, 2025). "In addition, the distribution of serum FGF23 levels as the function of tumor staging and grading failed to meet the criteria of a good diagnostic test." (PMID 32570721, 2020). "This may, in large part, be due to the fact that KL acts as a tumor suppressor in various types of cancer, whereas such a function is not established for FGF23." (PMID 33520985, 2020). "Therefore, quantification of serum FGF23 level is critical to settle the diagnosis and the existence or absence of residual tumor." (PMID 23251177, 2012). "Initially, the right ovary was removed but did not contain the FGF-23-secreting tumor." (PMID 21611969, 2011). "They speculated that in such cases the tumour either secreted inactive or insufficient FGF-23, or even none whatsoever." (PMID 21410940, 2011). "68Ga-DOTATOC PET/CT could visualize a 111In-pentetreotide-negative FGF23-producing tumor." (PMID 39866919, 2025). "However, the expression of FGF23 (log2 fold change; 0.031) and FGFR1 (log 2 fold change; 1.59) was not changed significantly by the transfection in addition to the KL/KLB, SPP1, SFRP4, and MEPE, even though the tumor mRNA showed relatively high FPKM in these genes." (PMID 36686800, 2022). "Neither FGF23, nor 1,25 dihydroxy vitamin D levels were routinely measured in our patient cohort and the expected number of neoplasms in our relatively young population of individuals is uncertain, so it is not possible to establish whether this is a significant association or a chance finding." (PMID 29460029, 2018). "A case showed a much higher secretion of FGF-7 in comparison with FGF-23, which enabled the clinician to correctly localize the FGF-7 producing tumor through an FGF-7 gradient rather than an FGF-23 gradient." (PMID 37623022, 2023). "Our analyses showed that tumor size did not correlate with serum phosphate, TmP/GFR or 1,25-dihydroxyvitamin D but it was significantly correlated with FGF23 levels." (PMID 35857061, 2022). "Interestingly, a significant correlation between SUVmax of the culprit tumor at SSTR-PET/CT and serum FGF23 levels was not reported." (PMID 31861469, 2019). "The obtained data reveal novel mechanisms of FGF23+ PMT development involving MCs and may be used in translational medicine by supporting the development of new algorithms for personalized therapies as alternatives to surgical treatment when tumour removal is not feasible." (PMID 40981193, 2025).
kidney disease (140 papers, 2010 to 2026). "High levels of FGF23 have been linked to worse kidney disease, heart problems, and an even higher risk of death." (PMID 40559238, 2025). "Vervloet et al39 have described a positive association between FGF23 and smoking in a group of 604 patients with moderate to severe kidney disease." (PMID 38124483, 2024). "CKD patients have elevated serum levels of fibroblast growth factor (FGF), of which FGF23 has a strong dose-dependent association with cardiovascular morbidity, chronic inflammation and progression of kidney disease." (PMID 39329105, 2024). "The results of this study indicate a positive association of FGF23 levels with increased progression of kidney disease." (PMID 39433982, 2024). "Alterations in mineral metabolism, including those involving klotho deficiency and increased circulating FGF23 levels, have been linked to kidney disease." (PMID 36674838, 2023). "High FGF-23 levels have been suggested to be strongly correlated with serum creatinine levels and associated with kidney disease progression." (PMID 36362179, 2022). "In this population, two additional markers of sMBD, FGF23 and osteopontin, were associated with kidney disease and also strongly associated with mortality." (PMID 36819194, 2022). "Epidemiological studies have repeatedly reported that FGF23 is an important factor associated with increased risk of progression of kidney disease, loss of kidney graft function, cardiovascular disease and mortality." (PMID 33233840, 2020). "The relationship between elevated FGF-23 levels with AF and left ventricular function, independently of kidney disease, was unclear until now in the literature, showing association in some cohorts, but not in others." (PMID 30615112, 2019). "In recent years, many publications have demonstrated that serum levels of FGF-23 are associated with increased mortality, renal disease progression and development of CVD." (PMID 28045952, 2017). "Elevated FGF23 levels are associated with multiple adverse outcomes including kidney disease progression, cardiovascular events and death." (PMID 27495287, 2016). "Moreover, hormonal fluctuations associated with kidney disease, such as modifications in erythropoietin and fibroblast growth factor-23 (FGF-23) concentrations, can impact glucose regulation." (PMID 37868469, 2023). "Remarkably, correcting ID might be associated with a reduction in fibroblast growth factor 23 (FGF23), which was linked with worse clinical outcomes in both HF and renal disease." (PMID 35011874, 2021). "There is emerging evidence that FGF23 is closely associated with both cardiovascular and kidney diseases, indicating that FGF23 may play a role in the pathophysiology of CRS." (PMID 33460402, 2021). "Whether FGF23 can induce renal injury by targeting other cell types than fibroblasts as well as the spectrum of renal diseases that might involve FGF23 as a causative kidney-damaging factor remains to be established." (PMID 29770125, 2018). "In kidney disease, higher circulating levels of the mineral-regulating hormone fibroblast growth factor (FGF)-23 are predictive of disease progression but direct pathogenic effects on the kidney are unknown." (PMID 28611350, 2017). "In addition, elevated circulating FGF23 concentrations are independently associated with more rapid progression of kidney disease and renal allograft loss." (PMID 22970174, 2012). "The difference between the associations of FGF-23 with outcomes observed from conventional epidemiological studies versus using genetic approaches highlights a key challenge to epidemiologists performing observational studies where it is important to adjust for any degree of kidney disease." (PMID 36719157, 2023). "However, it is intriguing to speculate that a decrease in the FGF23 serum level may indeed be beneficial as FGF23 has been shown to go up in various cardiovascular and renal diseases and in particular in those associated with inflammation." (PMID 33517471, 2021).
kidney disease (continued). "FGF23 production by osteocytes, important for maintaining phosphate homeostasis, is typically elevated in patients with kidney disease." (PMID 39950977, 2025). "Linear regression models were used to examine the independent associations of FGF23 with six cardiac 2D-STE indices adjusting for demographics, cardiovascular risk factors, markers of kidney disease severity, and inflammation." (PMID 39560998, 2025). "Increased circulating FGF23 concentrations are associated with LVH, kidney disease progression, and mortality in patients with dialysis, predialysis CKD, or non-CKD, independent of risk factors, such as high phosphate and parathyroid hormone concentrations." (PMID 36895836, 2023). "Specifically, Klotho was required to promote excessive FGF23 expression by long bones during kidney disease." (PMID 36967231, 2023). "Increasing levels of FGF‐23, serum phosphate, and serum CaxP product are important parameters to evaluate stage and progression of kidney disease." (PMID 38053473, 2023). "To assess a potential role of Memo1 in kidney disease‐driven Fgf23 expression, we therefore challenged mice of both genotypes with AKI induced by intraperitoneal injection of 240 mg/kg of body weight folic acid." (PMID 36967231, 2023). "Bone‐intrinsic autocrine or paracrine signaling of FGF23 via FGFR/Klotho was reported to be important for the FGF23 increase in experimental kidney disease." (PMID 36967231, 2023). "Clinical studies have demonstrated that high serum FGF23 concentration can be used to diagnose kidney disease progression, specifically in the initial stages of diabetic nephropathy." (PMID 37108717, 2023). "These investigations on FGF23 demonstrate its multifaceted role in disease progression and how its blockade can be beneficial in eliminating metabolic/mineral, kidney disorders, and cancer regression." (PMID 37108717, 2023). "Increased serum FGF23 is a well-established predictor of mortality in renal disease, but recent findings linking increased levels to hepatic and cardiac diseases have suggested that other organs are sources of FGF23 or targets of its effects." (PMID 35231062, 2022). "The excess lipocalin-2 in kidney disease increases bone production of FGF23 and serum FGF23 levels, which contributes to the progression of the disorder." (PMID 36157448, 2022). "Increased levels of FGF23 and metabolic acidosis are detrimental to health, and they contribute to the progression of renal disease and survival." (PMID 35268016, 2022). "The overwhelming majority of these data refer to patients already diagnosed with a kidney disease, which is widely known as an initial trigger to the elevation of FGF23." (PMID 35736431, 2022). "In many kidney diseases, the phosphorus excretion declines, and as compensation, the level of FGF-23 increases." (PMID 35159318, 2022). "Increased levels of PTH and FGF-23 mediate increased phosphate excretion per functioning nephron in early stage renal disease." (PMID 35204237, 2022). "Defining mechanisms of excessive FGF23 production and its pathophysiological effects are of importance to a variety of tissues and the relationship of renal disease to diseases in other organs." (PMID 35231062, 2022). "On the other hand, in an FA-induced renal disorder model, a further increase in serum FGF23 concentration was observed in Tmem174−/− mice." (PMID 35428804, 2022). "FGF-23 is a phosphaturic hormone that is elevated in the later stages of kidney disease, followed by a reduction in 1,25-dihydroxy-vitamin D (1,25 [OH]2D) and an increase in parathyroid hormone (PTH)." (PMID 36232497, 2022). "Our analyses provide a long-sought building block to strengthen a pathophysiological concept that integrates both RAS activation and excess in FGF23 as a common final stretch in heart and kidney disease." (PMID 35201364, 2022).
kidney disease (continued). "Although FGF23 expression in the healthy kidney appears to be very low, increased renal FGF23 expression has been noted in several models of kidney disease." (PMID 33989306, 2021). "Phosphates have traditionally been established as the main target to control in renal disease, with FGF-23 having been considered a “secondary player” that has the apparently unique role of reducing serum phosphate levels." (PMID 34867481, 2021). "Reports indicate that a progressive increase in FGF23 predicts rapid progression of kidney disease and mortality." (PMID 33498560, 2021). "It has been revealing that FGF-23 is a novel independent predictor of the progression of renal disease in patients with macroalbuminuric diabetic nephropathy." (PMID 34065223, 2021). "In the Mild to Moderate Kidney Disease study, FGF-23 predicted the progression of CKD independently of other factors, such as glomerular filtration rate (GFR), phosphate, and PTH4." (PMID 33060834, 2020). "The increased circulating FGF23 is still able to execute its function in the injured kidney and thereby maintains a normal plasma level of phosphate until late stage of kidney disease." (PMID 33233840, 2020). "Plasma levels of FGF23 increase early in kidney disease before derangements in plasma phosphate and PTH." (PMID 33233840, 2020). "As such, induction of extra-skeletal FGF23 from bone marrow, kidney, and heart has been shown in renal disease." (PMID 31236663, 2019). "In conclusion, the rapid, CKD‐induced rise in plasma FGF23 and the similar decrease in cardiomyocyte calcium transients in modeled kidney disease and following 1‐week treatment with FGF23 indicate that FGF23 partly mediates cardiomyocyte dysfunction in CKD." (PMID 29611320, 2018). "Higher FGF-23 is perceived as one of the earliest markers of kidney disease, reaching very high levels at the time of ESRD." (PMID 29698460, 2018). "Differences between Hyp and kl/kl mice regarding characteristics of cardiovascular and kidney disease, cardiac FGF23/FGFR4 system, and parameters of mineral metabolism." (PMID 29977226, 2018). "The first cohort study focusing on FGF23 was the Mild-to-Moderate Kidney Disease (MMKD) Study that enrolled 227 patients." (PMID 29270765, 2018). "In CKD, as the renal disease advances, a decline in Klotho expression has been reported whereas FGF-23 expression increases progressively; high serum phosphate and PTH and low vitamin D levels accompany these changes." (PMID 30370270, 2018). "Lower levels of 25 and 1,25 vitamin D have been associated with elevated serum level of Fibroblast growth factor 23 (FGF-23) and decreased kidney CYP27b1 due to kidney disease progress." (PMID 28665937, 2017). "Taken together these findings suggest a role for FGF23 in kidney disease outside of the mineral bone disease entity and strengthen the rationale for therapeutic targeting of off-target FGF23 effects in CKD." (PMID 28611350, 2017). "Laboratory measurements including fibroblast growth factor-23 and sclerostin, and quality of life assessed with the Kidney Disease Quality of Life-Short Form are also studied." (PMID 28460640, 2017). "In uremic rats calcitriol should be further reduced by the decrease in renal mass and by the elevation in FGF23 secondary to kidney disease." (PMID 29281993, 2017). "Fibroblast growth factor-23 (FGF23), a phosphate(Phos)-regulating hormone, is abnormally elevated in hypophosphataemic syndromes and an elevated FGF23 is a predictor of mortality in kidney disease." (PMID 26453792, 2016). "These include renal disease and arterial calcification, and an elevated FGF23 concentration is a predictor of mortality in these patients." (PMID 26453792, 2016). "In a cohort of 227 patients with CKD, FGF23 was an independent predictor of kidney disease progression after a median of 53 months follow up." (PMID 27495287, 2016).